EGFR (epidermal growth factor receptor)
Diseases named in the same sentence as EGFR in open-access papers (continued):
Sharing a sentence is not in itself a finding about the gene and the disease.
tumor (continued). "This study identifies the tumor size, nodal status, and the EGFR score as independent predictors for poorer DFS and OS, while adjuvant chemotherapy and radiotherapy were associated with improved survival rates." (PMID 40150035, 2025). "We also took advantage of the cross-reactivity of the anti-PD-L1 and anti-EGFR Nanofitins against the murine targets to demonstrate the in vivo anti-tumor activity of the bispecific molecule in a syngeneic immunocompetent model." (PMID 40305184, 2025). "In CRC, it methylates EGFR at R198/R200 in the extracellular domain, enhancing ligand binding and receptor activation to drive tumor cell proliferation." (PMID 41204384, 2025). "We expect that the treatment paradigm will gradually shift from single agents targeting EGFR to genomically informed combination regimens designed to address tumor-specific escape mechanisms." (PMID 41018114, 2025). "Core genes were identified as Hub-EGFR.Sig to predict the prognosis of cancers and to understand the crosstalk between EGFR and the tumor immune microenvironment (TIME)." (PMID 40574864, 2025). "Treatment of HNSCC mouse xenografts with monoclonal antibodies targeting both IGF-1R and EGFR has provided a significant reduction in tumor volume." (PMID 40560045, 2025). "The molecular profiling of tumor cells demonstrates extensive tumor heterogeneity, which plays a critical role in the emergence of EGFR-TKI resistance." (PMID 40003951, 2025). "Finding inhibitors against both forms of EGFR increases the therapeutic scope ensuring comprehensive inhibition, minimizing resistance and tumor progression." (PMID 40344575, 2025). "Anti-Epidermal Growth Factor Receptor (EGFR) antibodies can competitively bind to EGFR, reducing the secretion of immunosuppressive cytokines by tumor cells (such as vascular endothelial growth factor, IL-10)." (PMID 40872965, 2025). "Taken together, we demonstrated that the induction of AREG by E2 contributes to EGFR activation, which then affects cell proliferation and tumor growth." (PMID 40422206, 2025). "We analysed 142 samples from 39 KRAS wild‐type fully resected primary tumours of metastatic CRC patients undergoing anti‐EGFR therapy (in first‐, second‐ or third‐line treatment), covering the entire tumour, invasion front and six morphological regions." (PMID 40302146, 2025). "EGFR influences numerous pathways and genes that shape the tumor microenvironment and drive tumor development." (PMID 40859900, 2025). "The combination of ICIs with anti-EGFR antibodies has demonstrated the potential for synergistic anti-tumor activity." (PMID 40058234, 2025). "For instance, gold nanoparticles have been used to effectively deliver various anti-CRC therapies to tumor cells, including chemotherapy drugs and anti-EGFR inhibitors, resulting in enhanced anticancer drug efficacy." (PMID 40076613, 2025). "Wild-type EGFR overexpression transformed cells in vitro and induced tumorigenesis in vivo in transgenic mouse models, with tumor maintenance dependent on the continuous expression of EGFR." (PMID 41227364, 2025). "Results from this trial were promising, with EGFRvIII-specific immune responses effected in all patients, and EGFR-expressing tumor cells eradicated in almost all patients." (PMID 40507329, 2025). "It promotes oncogenesis through the shedding of membrane-bound precursors of growth factors and cytokines, leading to activation of signaling pathways such as Notch and EGFR, which promote tumor cell proliferation, migration, and invasion." (PMID 41050403, 2025). "Upon cellular uptake, the GSH-cleavable linkage breaks, releasing the active PROTAC to degrade EGFR and trigger tumor cell apoptosis." (PMID 40284496, 2025).
tumor (continued). "Among 35 tumors obtained from patients with EGFR-mutated NSCLC treated with EGFR-TKIs, the present tumor showed relatively increased inflammatory cells, including exhausted CD4 and CD8 positive cells and M1-like macrophages, compared to other tumors." (PMID 41001033, 2025). "GEM models have revealed key insights into tumor invasion, microenvironment interactions, and therapeutic targets, including EGFR-driven migration and oncostream formation." (PMID 40940872, 2025). "EGFR imaging showed high preclinical receptor-specific specificity, whereas clinical performance revealed cetuximab tumor accessibility, which was undetectable by FDG PET, with significant variability between patients." (PMID 41211421, 2025). "CAFs, one of the most abundant components within TME, promote tumor malignancy and confer anti-EGFR therapy resistance through multiple mechanisms, including ECM remodeling, secretion of soluble molecules, exosome vesicle delivery, and metabolic crosstalk." (PMID 40362183, 2025). "PEGylated liposomal Dox (Caelyx) targeted to EGFR (αEGFR-Caelyx) was found to accumulate and penetrate the inner region of tumor spheroids with tumor-bearing mice intravenously treated with αEGFR-Caelyx, showing significantly decreased expansion of the tumor." (PMID 40124344, 2025). "Microvascular density is the clinical standard for evaluating tumor angiogenesis, which negatively affects the outcome of antitumor therapy with epidermal growth factor receptor-tyrosine kinase inhibitors (EGFR-TKI)." (PMID 41226923, 2025). "Given its prominent role in tumor biology, EGFR has become a compelling target for CAR T cell therapy." (PMID 41516067, 2025). "Tumor sections from patients with CRC were subjected to EGFR immunofluorescence (IF) staining to explore the relationship between EGFR internalization and cetuximab therapeutic efficacy." (PMID 39560161, 2025). "In summary, DPP4 was a significantly up‐regulated marker in both DTP and c‐DTP cells, with elevated levels also observed in patient tumor tissues treated with EGFR‐TKIs." (PMID 40479551, 2025). "The presence of this alteration, previously confirmed as an EGFR mutation before treatment, suggests that WES can provide complementary information on the genomic landscape of the tumor." (PMID 41303594, 2025). "This discovery further highlights the pivotal role of tumor heterogeneity in the development of acquired resistance to EGFR-TKIs." (PMID 40003951, 2025). "EGFR-mutant tumours also secrete elevated IL-6, which impairs T and NK cell activity, further skewing the microenvironment toward immunosuppression." (PMID 40647497, 2025). "NGS can identify actionable mutations, such as EGFR, KRAS, and ALK mutations, that drive tumor growth, enabling more precise and effective treatment decisions." (PMID 39796742, 2025). "In conclusion, tumor cell heterogeneity plays a pivotal role in driving the development of EGFR-TKI resistance through various mechanisms." (PMID 40003951, 2025). "First line targeted monotherapies (e.g. EGFR antagonists, ALK inhibitor, etc.)and immunotherapies (PD1/PDL1 inhibitors) have been well-established in tumours expressing targetable mutations, and has become the standard of care." (PMID 40486071, 2025). "Among these approaches, dual inhibition of epidermal growth factor receptor (EGFR) and tumor-associated human carbonic anhydrases (hCA_IX and hCA_XII) has emerged as a promising direction due to their critical roles in cancer progression." (PMID 40906750, 2025). "The frequent overexpression of EGFR and subsequent activation of this signaling cascade contribute significantly to tumor development and treatment challenges." (PMID 40723400, 2025). "CAR-NK cells also target solid tumor antigens such as HER2, EGFR and mesothelin, showing effective tumor infiltration and anti-tumor responses." (PMID 40155973, 2025). "In HNSCC models (e.g., HNSCC cell lines), T cell-dependent lysis of Tumor Cells was induced by the EGFR/CD3 bispecific antibody." (PMID 41333481, 2025).
tumor (continued). "Although EGFR and KRAS are closely linked within their signaling pathways, harboring oncogenic mutations in these genes differently affects prognosis, tumor biology, histological differentiation and immunogenicity." (PMID 40809430, 2025). "Erlotinib normalizes tumor blood vessels by inhibiting the EGFR/ERK/AKT axis to enhance intra-tumoral oxygenation." (PMID 40235732, 2025). "Key driver mutations, such as EGFR and KRAS, are generally clonal and emerge early in tumor evolution, being present in both primary and metastatic sites." (PMID 41158851, 2025). "miR-651-5p antagonists increase immune cell infiltration and enhance the anti-tumor effect of PD-1 inhibitor, suggesting a new combination therapy to improve the efficacy of immunotherapy in EGFR-mutant NSCLC patients." (PMID 40002895, 2025). "These antiglioma effects of Kae have been confirmed in vivo using xenograft tumor nude mice models, demonstrating that Kae effectively inhibits tumor growth and enhances the antitumor effects of Gef by targeting the EGFR/SRC/STAT3 signaling pathway." (PMID 41009025, 2025). "Overall, EGFR pathway-related metabolic changes reflect comprehensive metabolic reprogramming of tumor cells." (PMID 40486879, 2025). "Knockout or knockdown of CMTM4 in tumor cells resulted in inhibition of EGFR signaling, mTOR and PI3K/Akt pathways." (PMID 39948411, 2025). "Larger NP size (~20 nm) allowed the achievement of enhanced tumor affinity and targeting in EGFR-overexpressing xenografts, while maintaining efficient renal clearance." (PMID 39940134, 2025). "A431 tumor‐bearing mice showed high EGFR immunoreactivity within the tumor tissues, especially in the basal cell layer." (PMID 40830817, 2025). "Experimental studies have demonstrated that inhibiting the expression levels of EGFR and blocking its phosphorylation can suppress the release of exosomes from hypoxic tumor cells, thereby exerting significant therapeutic effects in the treatment of cancer." (PMID 40732366, 2025). "Drug testing on organoids has shown promising results, such as the reduction in tumor size with mTOSR complex inhibitor and EGFR kinase inhibitors, Everolimus and Afatinib, respectively." (PMID 40255860, 2025). "The oncogenic signaling pathway mutations consisted of KRAS, EGFR, and ALK/ROS1/RET mutations, which play crucial roles in cell proliferation and are associated with tumor aggressiveness and a higher risk of recurrence." (PMID 40507370, 2025). "Beyond identifying tumor burden, EGFR also modulates immune responses, including the expression of PD-L1 and immune cell infiltration, and is considered a surrogate marker for immune profiling." (PMID 41211421, 2025). "By conjugating the cetuximab antibody to the modified starch and using its ability to actively target overexpressed EGFR HNSCC tumor cells, we aim to achieve the targeting of our delivery system for precise therapeutic outcomes." (PMID 40666030, 2025). "MMP28 facilitates tumor progression via TGF-α/EGFR axis activation, where elevated MMP28 expression enhances TGF-α maturation to drive oncogenic signaling and metastasis." (PMID 40486509, 2025). "Our findings put forward a new viewpoint on the interactions between EpCAM and EGFR in the membranes of stem cells and even tumour cells and provide potential targets for the CTE therapy." (PMID 39939830, 2025). "Several studies have shown that EGFR-mutated NSCLC is generally less responsive to ICIs,28,29,30 potentially due to the immunosuppressive or weakly immunogenic tumor microenvironment." (PMID 41446744, 2025).
tumor (continued). "In terms of nanoprobe-based biomarker detection, nanomaterials are employed to detect circulating tumor cells (CTCs) and tumor biomarkers such as folate receptors, EGFR, and HER2, enabling early diagnosis and prognostic assessment." (PMID 40732539, 2025). "Reactivation can result at least partly from increased antigen presentation by APCs, upregulation of HLA-I on tumor cells, and alleviating T-cells’ inhibition after treatments such as radiotherapy, EGFR TKIs, and anti-PD-1 immunotherapy." (PMID 39852160, 2025). "TNC, for instance, has been shown to enhance the activation of growth factor signaling pathways such as EGFR and Wnt/β-catenin, thereby promoting increased tumor cell survival and division." (PMID 40699660, 2025). "Since EGFR is known to play a key role in the tumor microenvironment, a study investigated the effects of EGFR system on MSCs following stimulation with EGFR ligand." (PMID 41227364, 2025). "In our study, we discovered a substantial positive correlation between STARD4 and EGFR mRNA expression in tumor tissue samples obtained from HCC patients." (PMID 40831538, 2025). "Bispecific ADCs that co-target antigens such as HER2 and EGFR address tumor heterogeneity and improve targeting precision." (PMID 41184856, 2025). "To address the presence of NK cells in the tumor microenvironment, we analyzed tumors derived from cSNX1.3 (n = 9) and cPTD4 (n = 9) treated mice with for NK cell infiltration and EGFR expression." (PMID 39521886, 2025). "Masked TCEs targeting different tumor antigens, including EGFR, retained potent antitumor efficacy while markedly reduced toxicity in vivo, and are progressing into clinical trials." (PMID 41341587, 2025). "The patient-derived tumor in Case 8 was found to have EGFR copy number gain and did demonstrate some response to the EGFR inhibitor erlotinib." (PMID 41155119, 2025). "The table summarizes polymer/tumor-specific patterns and implicated agents (e.g., doxorubicin, taxanes, HER2/EGFR inhibitors), emphasizing the need to measure MP exposure in preclinical efficacy studies." (PMID 41378310, 2025). "As anticipated, the treatment significantly reduced the number of tumor cells that presented EGFR over-activation in neoCORs." (PMID 39996764, 2025). "The frequency of EGFR mutations in NSCLC varies according to ethnicity, smoking status, and tumor histology, ranging from 10 to 15% in Western populations to up to 50% in certain Asian cohorts." (PMID 41155830, 2025). "Considering the favorable results regarding cell transduction and the cytotoxic effects on EGFR+ tumor cells, this study presents a promising approach to CAR-based platforms through the transduction of PBMCs." (PMID 40002679, 2025). "Inspection of variants in genes linked to anti‐EGFR therapy (KRAS, BRAF, NRAS, PTEN and PIK3CA) revealed variability across tumours and fractions." (PMID 40302146, 2025). "Several studies have shown that ginsenoside Rg3 shows a significant regulatory effect on EGFR and can reduce EGFR expression and activation in a variety of tumor cells." (PMID 40732366, 2025). "The combination of this compound with cisplatin produced a synergistic anti-tumor effect, significantly reducing the phosphorylation levels of EGFR and its downstream proteins AKT and ERK." (PMID 40333837, 2025). "ERRFI1 functions as a regulator of EGFR-mediated signaling and is involved in tumor development and chemoresistance in CRC." (PMID 39905540, 2025).
tumor (continued). "CDx biomarkers (including BRAF, EGFR, PIK3CA, and RAS mutations) and other tumor profiling biomarkers (including clinically relevant alterations and TMB) were represented in marker positive samples diluted with lineage matched marker negative samples." (PMID 40804002, 2025). "EGFR inhibitors (EGFRIs) are used as targeted therapies for cancer, blocking EGFR signaling and reducing tumor growth." (PMID 39966897, 2025). "Osimertinib is a third-generation irreversible epidermal growth factor receptor tyrosine kinase inhibitor (EGFR-TKI) that selectively targets EGFR-TKI-sensitive mutations, thereby inhibiting tumor cell proliferation, migration, and invasion." (PMID 40538542, 2025). "The resulting EGFR activity subtypes and entailed phenotypes, which differentially contribute to tumor progression, provide molecular rationales for varying patients ́ responses to treatment." (PMID 40121428, 2025). "These modifications, which are crucial for tumor growth and increase resistance to targeted treatments like EGFR-TKIs, include changes in glycolysis, oxidative phosphorylation, and lipid metabolism in NSCLC." (PMID 41310903, 2025). "Combination of antibody and chemotherapy targets the tumor specific receptors such as anti-EGFR/VEGF antibody for increased improvement in tumorigenesis." (PMID 40230862, 2025). "The amplification of the EGFR and an elevated incidence of EGFRvIII mutations in GBM, and they associate these findings with aggressive tumor characteristics." (PMID 40867215, 2025). "Initial findings indicate that CAR-T cells hold potential in targeting tumor-specific antigens, such as the epidermal growth factor receptor (EGFR), which is commonly overexpressed in HNSCC." (PMID 40312353, 2025). "Collectively, these results demonstrate that cetuximab-IRDye800CW generates strong and tumor-specific fluorescence in multiple EGFR-high models, thereby confirming its ability to target EGFR in vivo." (PMID 41346398, 2025). "Considering the heterogeneous function of Hub-EGFR.Sig in pan-cancer, we subsequently performed survival analysis across tumor types." (PMID 40574864, 2025). "In EGFR-mutated NSCLC, Oligo-PD has been proposed to be histologically heterogeneous, with coexisting tumor cells that are resistant and sensitive to EGFR-TKIs." (PMID 40647500, 2025). "Together, these data show a direct role for tumor cell nuclear EGFR in modulating NK cell activity, although other impacts on the immune system are likely." (PMID 39521886, 2025). "Studies have demonstrated that following the development of resistance to EGFR-TKIs, the level of tumor vascular endothelial growth factor (VEGF) increases, reducing tumor cell dependence on the EGFR signal and increasing dependence on the VEGF pathway." (PMID 40277759, 2025). "These molecular alterations not only drive tumor progression but also predict poor response to EGFR-targeted therapies, significantly influencing both prognosis and treatment outcomes." (PMID 40940901, 2025). "The EGFR content in tumors corresponded to the tumor weight, and the sequential administration group had the lowest EGFR content." (PMID 40732366, 2025). "EGFR and KRAS mutations in tumor cells can modulate the function of TILs through complex signaling networks, including secretion of chemokines and cytokines present in the TME/TIME." (PMID 40524071, 2025). "Cetuximab is a monoclonal antibody targeting EGFR, demonstrating the ability to inhibit tumor proliferation in cervical tumor cell lines." (PMID 41463185, 2025).